AR (androgen receptor)
Diseases named in the same sentence as AR in open-access papers (continued):
Sharing a sentence is not in itself a finding about the gene and the disease.
prostate carcinoma (continued). "ELF5 binds to AR in androgen receptor (AR)-activated prostate cancer and negatively regulates its transcriptional activity or inhibits SMAD3 activation." (PMID 33742100, 2021). "In prostate cancer, the mainstay of therapeutic approaches is inhibition of the androgen receptor; however, resistance occurs within two years." (PMID 34439974, 2021). "There is a lack of understanding of the similarities and differences between AR regulated cellular phenotypic changes in neurons and prostate cancer cells." (PMID 33572108, 2021). "GRβ was shown to stimulate the proliferation of LNCaP-ARA70β prostate cancer cells and to have a cross-talk relation with AR." (PMID 34638264, 2021). "Later in the disease course, prostate cancer cells can become androgen independent and, eventually, even AR independent." (PMID 34262149, 2021). "In prostate cancer cells Foxo1 is recruited by ligand activated AR to the promoter of AR target genes." (PMID 33816477, 2021). "A small molecule inhibitor of LSD1 (GSK2879552) was effective alone and in combination with AR-targeting enzalutamide in prostate cancer xenograft models." (PMID 33980863, 2021). "In this study, we found that PAQR6 expression was enhanced by DHT stimulation in prostate cancer LNCaP cells, which was blocked by AR antagonist Bicalutamide." (PMID 34572596, 2021). "Together, we find that co-inhibition of the AR and MAPK pathway activity is synergistic in prostate cancer cells carrying a BRAF mutation." (PMID 34211036, 2021). "In prostate cancer, persistent exposure to androgen deprivation leads to a decrease in androgen receptor signaling." (PMID 34771460, 2021). "While many treatments for prostate cancer suppress the androgen receptor it becomes reactivated during disease progression." (PMID 34737261, 2021). "In fact, a number of reports indicate that DNA damage can be induced in prostate cancer cells by overstimulation of AR activity." (PMID 33112375, 2021). "Androgen receptor (AR), a member of nuclear receptor family, plays vital roles in the development of prostate cancer." (PMID 33621955, 2021). "Even for castration resistance prostate cancer (CRPC) cases, prostate cancer progression is also substantially dependent on AR signaling pathway." (PMID 33219721, 2021). "BAG1-L inhibition is a promising treatment of AR-dependent prostate cancer as BAG1-L knockdown decreased cancer cell proliferation by reducing AR signaling." (PMID 34831344, 2021). "In an analogous manner like the one observed in ERα-positive breast tumor cells, RSV inhibits DNA synthesis and modulates cell cycle progression in androgen receptor positive prostate cancer cells." (PMID 33669559, 2021). "In this review, we will look into the existing methods to study treatment resistance to androgen receptor targeted therapies in prostate cancer." (PMID 33671614, 2021). "For instance, PRMT5 epigenetically activates the transcription of the androgen receptor and facilitates prostate cancer cell growth." (PMID 33495409, 2021). "Recent work from the Culig laboratory established PIAS1 as a positive feedback regulator of AR signaling, which is achieved through enhanced AR stabilization in prostate cancer." (PMID 33572160, 2021). "In line with our prediction, studies show that ICT can target ESR1 and AR to control the growth of advanced breast and prostate cancer, which confirms the predictive accuracy of our approach." (PMID 33460401, 2021). "AR-V7 lacks the LBD, is constitutively active and confers resistance of prostate cancer cells to agents targeting the classical AR signaling pathway." (PMID 33737681, 2021). "VPC-220010 inhibits AR-mediated transcription of full length and truncated variant ARV7, downregulates AR response genes, and selectively reduces the growth of both full-length AR- and truncated AR-dependent prostate cancer cell lines." (PMID 34298700, 2021).
prostate carcinoma (continued). "For example, PRMT5 is a potential target for the inhibition of prostate cancer growth as it potentiates prostate cancer tumorigenesis by methylating AR genes important for tumor progression." (PMID 33440687, 2021). "In particular, some ONR members (including RORγ, TR2, TR4, COUP-TFII, ERRα, DAX-1 and SHP) exhibit multiple cross-talks with AR signaling in both normal and malignant prostatic cells, indicating their intricate interplay in prostate cancer progression." (PMID 33750894, 2021). "Recently MID1 was found to up-regulate AR protein levels in several prostate cancer cell lines and its expression was negatively regulated by androgen signaling." (PMID 34276780, 2021). "Adenocarcinoma accounts for the vast majority of prostate tumours and is usually positive for expression of the androgen receptor (AR)—the key therapy target in prostate cancer." (PMID 34535657, 2021). "Using an advanced, robust quantitative proteomic analysis, we profiled the prostate cancer cell proteome induced by the two AR antagonists/anti-androgens, Bicalutamide and Enzalutamide." (PMID 33572476, 2021). "With respect to the crucial role of the androgen receptor in prostate cancer, we have performed additional experiments with several AR-positive cell lines (LNCaP, C4-2, LAPC4, and 22rv1)." (PMID 33799604, 2021). "In short, it suggests that some downstream regulatory factors in the AKT and AR interaction network play a vital role in prostate cancer metastasis and are potential targeting molecules for prostate cancer metastasis treatment." (PMID 33377281, 2021). "On the other hand, cytoplasmic hnRNPK was proposed to down‐regulate AR mRNA translation in prostate cancer." (PMID 33931969, 2021). "In vitro and in vivo prostate cancer model systems showed inhibition of androgen receptor (AR)/ prostate-specific antigen (PSA) signaling." (PMID 34099820, 2021). "Prostate cancer among black men is known to have specific molecular characteristics, especially the androgen receptor or enzymes related to the androgen metabolism." (PMID 33446131, 2021). "A recent NCI workshop on Lineage Plasticity in AR-independent prostate cancer highlighted an urgent need to identify novel therapeutic targets to treat CRPC that bypasses AR-directed therapies." (PMID 33471819, 2021). "Zeta55 reduces the growth of AR-overexpressing VCaP prostate cancer cells both in vitro and in a CRPC xenograft model." (PMID 33621955, 2021). "ATG4D affects the biological behavior of prostate cancer by regulating the activity of androgen receptor." (PMID 33604190, 2021). "They show that combining Pin1 inhibition with ralaniten compounds that bind to the AR N-terminal domain has enhanced antitumor activity on castration-resistant prostate cancer in xenografts, suggesting therapeutic potential." (PMID 33753863, 2021). "This maintains a strong rationale for researching novel active delegates that target AR down-regulation to cure or prohibit developed the progression of prostate cancer." (PMID 34073059, 2021). "Co-regulation of transcription by AR and FOXA1 in prostate cancer is associated with reprogrammed binding of AR and oncogenic patterns of gene expression that are essential for AR-driven proliferation." (PMID 33596994, 2021). "To do this, we treated two unrelated AR-positive prostate cancer cell lines, LAPC4 and 22RV1, with the PIM1 inhibitor SGI-1776." (PMID 34697370, 2021). "TOBC is able to reduce the viability of the androgen sensitive (AR+) prostate cancer cells LNCaP by almost 70% after 48 h, suggesting TOBC antitumoral activity." (PMID 34885717, 2021). "Next, additional proliferation experiments further verified that nobiletin more significantly induced the growth inhibition of AR/AR-V7-positive prostate cancer cells." (PMID 34548474, 2021). "Resveratrol has shown its chemopreventive potential via targeting the androgen receptor axis, as shown in various in vitro models of prostate cancer." (PMID 33807174, 2021).
prostate carcinoma (continued). "Our epigenomic analyses focused on androgen receptor (AR), which is a key oncogenic driver in prostate cancer, the AR pioneer factor FOXA1, chromatin insulator CCCTC‐Binding Factor, as well as for modified histones H3K27ac and H3K27me3." (PMID 33576154, 2021). "In 2019, PROTAC ARV-110, which targets the androgen receptor (AR) for degradation in prostate cancer, has been approved by the FDA for phase I clinical trials." (PMID 34485285, 2021). "β-HCH was already proven to act as an EDC by driving AR nuclear translocation and transcriptional activation in the AR-positive prostate cancer cell line LNCaP." (PMID 34885717, 2021). "Recent advances in prostate cancer (PC) research unveiled real androgen receptor (AR) functions in castration-resistant PC (CRPC)." (PMID 33921329, 2021). "In prostate cancer, genetic changes in the AR result in resistance to androgen deprivation therapy (ADT), which is the first line therapy for patients with metastatic disease." (PMID 33652649, 2021). "The initiation of prostate cancer and the progression of the disease are driven by androgen receptor (AR) signalling, and androgen deprivation therapy (ADT) constitutes the backbone of systemic therapy for patients with advanced disease." (PMID 33106584, 2021). "SKP2 has been shown to also affect AR ubiquitination, but additionally its targets in prostate cancer include EZH2, p27, JARID1B, DAB2IP, AKT, BRCA2, ATF4, p27, p21, and Twist to regulate various cellular processes." (PMID 33572160, 2021). "The androgen receptor (AR) signaling pathway was shown to play an essential role in prostate cancer (PCa)." (PMID 34799554, 2021). "The traditional treatment of metastatic castrate-sensitive prostate cancer is the initiation of androgen deprivation, potentially in combination with chemotherapy or an androgen receptor inhibitor." (PMID 34829977, 2021). "TMPRSS2 has been widely studied in relation to prostate cancer and androgen receptor (AR) pathway because its expression is positively regulated by androgens through direct transcriptional regulation by AR." (PMID 35874037, 2021). "It has been reported that some adipokines, can suppress androgen sensitivity and the proliferation of androgen-dependent LNCaP cells (prostate cancer) through AR downregulation." (PMID 34066328, 2021). "We further discuss the identified S‐EVs miRNAs in the context of AR signalling axis in prostate cancer." (PMID 34434533, 2021). "In prostate cancer, AR is responsible for the activation of specific target genes that promote cancer initiation and progression." (PMID 33634124, 2021). "Remarkably, LGR4 inhibition confers radiation sensitivity only in AR-positive prostate cancer by regulating the activation of CREB1, a transcription factor that promotes DNA repair." (PMID 33946652, 2021). "Examination of pan-cancer functional genomics data for essentiality phenotypes for the top 5 hits revealed that AR is selectively essential for prostate cancer models as expected." (PMID 34326322, 2021). "On the basis of these biochemical requirements, the best candidate is represented by the hormone-responsive prostate cancer cell line LNCaP (AR+), which was already employed in our previous in vitro studies." (PMID 34885717, 2021). "As noted in Section 3, miR-200a, miR-200b, miR-200c and miR-141 are upregulated upon activation of androgen receptor signaling in prostate cancer cells." (PMID 34884985, 2021). "Because of the importance of the androgen/androgen receptor (AR) signaling pathway in prostate cancer initiation and progression, most basic and clinical research has been focused on the androgen/AR axis." (PMID 33535458, 2021).
prostate carcinoma (continued). "Yet, combinatorial use of PAM with other therapeutic strategies capable of transiting 'dormant' cells to the active state or leading them to apoptosis is recommended in practice to eradicate androgen receptor-independent prostate cancer cells." (PMID 34476012, 2021). "Stabilization of cellular HIP1 levels therefore plays an essential role for AR activation and AR‐dependent prostate cancer progression." (PMID 33219721, 2021). "During prostate cancer progression, N-Myc overexpression can potentiate the escape of tumors from AR and promote the development of CRPC and NEPC." (PMID 34523032, 2021). "AR, a steroid receptor transcriptional factor, plays pivotal roles in all stages of prostate cancer." (PMID 33946224, 2021). "The main drivers of prostate cancer progression, such as AR, PTEN/PI3K/AKT/mTOR, STAT3, NKX3.1 are influenced by PTMs, which changes their activity, expression, stability, and localization." (PMID 33572160, 2021). "Most primary prostate cancer cases show AR dependence and are responsive to androgen‐deprivation therapy." (PMID 33219721, 2021). "Since Huggins and Hodges first demonstrated the responsiveness of prostate cancer to androgen deprivation, it has been clear that prostate cancer is dependent on androgen and AR activation for growth and survival." (PMID 34630112, 2021). "The androgen receptor (AR) plays an important role in the development and progression of prostate cancer, due to the dependence of prostate cells on androgen for survival and growth." (PMID 33398073, 2021). "The androgen receptor (AR) plays a major role in prostate cancer development and progression and is the main target of PC therapy." (PMID 35011576, 2021). "We selected bergamottin for this study to monitor if it can be used as an CYP3A5 inhibitor to reduce AR activation and block prostate cancer growth." (PMID 34570813, 2021). "The initiation and progression of prostate cancer has been reported to be modulated by androgen receptor (AR) signaling." (PMID 35069196, 2021). "Having revealed the involvement of PRPF6 in AR signaling and growth of prostate cancer cells, we next examined the expression of PRPF6 in clinical prostate cancer samples." (PMID 33390843, 2021). "ADP-ribosylation of AR results in highly selective E3 recruitment and modulation of a subset of androgen-regulated genes in prostate cancer cells." (PMID 33976187, 2021). "AR-dependent mechanisms mediating drug resistance in prostate cancer can be at the level of resistance towards ADT, subsequently also resistance to AR antagonist treatment, towards inhibitors of androgen biosynthesis, or other pathways." (PMID 33810413, 2021). "These catechins induce prostate cancer cell death, suppressed agonist-dependent androgen receptor (AR) activation and AR-regulated gene transcription." (PMID 34858475, 2021). "Our results indicated the tumor-suppressing role of ZBTB38 in both AR-positive prostate cancer and CRPC cells." (PMID 34697293, 2021). "Celastrol-induced autophagy inversely correlates with AR expression levels, which in turn suppresses miR-101 expression, and thereby augments prostate cancer cell death." (PMID 34575981, 2021). "Our data demonstrated that PRPF6 plays a vital role in modulation of oncogenic AR signaling pathway and promotes the progression of prostate cancer and CRPC." (PMID 33390843, 2021). "Our data indicated that IRE1α, IL-6 and AR formed a positive feedback loop, and through which facilitated prostate cancer cell proliferation under androgen deprivation conditions." (PMID 34295814, 2021). "Alteration in Ruminococcaceae also occurred in prostate cancer patients treated with oral androgen receptor axis-targeted therapies." (PMID 32951160, 2021). "Reciprocal feedback between AR and PI3K/AKT occurs in prostate cancer and is implicated in loss of therapeutic efficacy." (PMID 34439133, 2021).
prostate carcinoma (continued). "AR re‐activation still remains a major challenge during treatment of castration‐resistant prostate cancer (CRPC) tumors that relapse after castration therapies." (PMID 33932081, 2021). "AKT3 protein level was examined by western blot analysis in two AR-positive, LNCaP and 22Rv1, as well as two AR-negative, DU145 and PC3, prostate cancer cell lines to confirm a correlation between AR signaling and AKT3 expression." (PMID 33540707, 2021). "To exclude the possibility that the highly increased expression of INMT in CRPC is model-specific, we established another PCa xenograft mouse model, in which an AR-positive and androgen-sensitive human prostate cancer cell line, LNCaP, was employed." (PMID 34587977, 2021). "One emerging strategy in effective treatment of the advanced forms of prostate cancer is to target drivers other than AR." (PMID 33916325, 2021). "Prostate cancer cells depend on the activity of the transcription factor androgen receptor (AR), which represents a major therapeutic target both in primary and advanced disease." (PMID 33664492, 2021). "Here, we review the mechanisms by which abnormal activities of ER and AR can dysregulate mRNA translation in breast and prostate cancer cells." (PMID 34209750, 2021). "The androgen receptor (AR) and its related signaling pathways play an important role in the development of prostate cancer (PCa)." (PMID 34833084, 2021). "The androgen receptor (AR) is critical for the progression of prostate cancer to a castration-resistant (CRPC) state." (PMID 34930302, 2021). "The mutual feedback between AKT and AR pathways plays a vital role in the progression and metastasis of prostate cancer." (PMID 33377281, 2021). "In prostate cancer, GR expression and activation occurs following exposure to androgen receptor blockade and it is suggested to be an important resistance mechanism driving castration resistant tumour progression." (PMID 33916028, 2021). "miR-31 negatively correlated with AR expression in a transcriptome analysis of prostate cancer tissues." (PMID 34940756, 2021). "The androgen receptor (AR) is the classical target for prostate cancer treatment, and estrogens and their receptors have recently been implicated in prostate cancer development and tumor progression." (PMID 33503805, 2021). "IL-23 secreted by MDSCs activating IL-23-IL-23R-RORγ axis of androgen receptor pathway in prostate cancer cells." (PMID 34095111, 2021). "Given the well-established role of FOXA1 in mediating AR transcriptional programs in prostate cancer, it is logical to predict that these two proteins also cooperate in molecular apocrine breast cancer to promote AR activation and target gene expression." (PMID 34680352, 2021). "This was in sharp contrast with both PSA and PSMA well-known prostate cancer markers, which were observed only in the LNCaP (AR expressing) and its lineage derivatives." (PMID 34099820, 2021). "Expect from miR-212, miR-361–3p was also reported to increase the enzalutamide sensitivity of prostate cancer via targeting the AR-v7." (PMID 34103477, 2021). "Differential expression has been determined in prostate cancer cells stimulated with androgen-induced or PKA-induced AR signaling by treating cells with DHT or FSK, respectively." (PMID 34680521, 2021). "The downregulation of the androgen receptor, synergy with flutamide, and the enhancement of radiosensitivity are the most interesting targets in the treatment of prostate cancer." (PMID 33546190, 2021). "FKBP51 and FKBP52 are linked to hormone-dependent cancers such as ERα-dependent breast and AR-dependent prostate cancer." (PMID 34831344, 2021). "PCAL7 was the lncRNA with the highest fold upregulation and significantly correlated with AR signaling during prostate cancer progression." (PMID 33219721, 2021).